CD44 (CD44 molecule (IN blood group))
Diseases named in the same sentence as CD44 in open-access papers (continued):
Sharing a sentence is not in itself a finding about the gene and the disease.
pancreatic cancer (continued). "The nanoparticles with a unique hollow structure selectively accumulated in both the xenograft pancreatic tumor and the orthotopic pancreatic tumor site following systemic administration possibly via size-reduction effect, and the CD44 mediated accumulation and internalization." (PMID 33364939, 2020). "Moreover, tumor-initiating cells (TICs) isolated from pancreatic cancer patient positive for CSCs markers EpCAM+/CD44+/CD24+ display high CAIX expression." (PMID 32560271, 2020). "To test whether cells had undergone dedifferentiation, we first assessed the expression of CD44 and EpCAM, as these represent the two most accepted CSC-associated markers in pancreatic cancer." (PMID 32764385, 2020). "CD44 existence implies the EMT in pancreatic cancer, cancer stem cells, or drug resistance." (PMID 31049070, 2019). "CD44 signaling is implicated in the dissemination of cancer cells during metastasis, which may occur during ADM or pancreatic cancer precursor lesion formation." (PMID 31490946, 2019). "CD44 is the principal cell surface receptor for HA, and it is widely present in many tumor cells such as pancreatic cancer cells, which suggests that it is promising and significant to use hyaluronan–CD44 interactions as potential targets for early cancer diagnosis." (PMID 31248076, 2019). "Finally, we further determine the expression of the pancreatic cancer markers CD44, CD326 and CxCR4 by immunofluorescence and by western blotting." (PMID 31388092, 2019). "Further, treated tumours showed a decreased expression of the pancreatic cancer marker CD44." (PMID 31388092, 2019). "Taken together, CD44 is a downstream target of miR-34a in pancreatic cancer." (PMID 29747682, 2018). "Human pancreatic cancer tissues express several CD44 isoforms." (PMID 29747682, 2018). "CD24 and CD44 are upregulated in human pancreatic cancer compared to chronic pancreatitis." (PMID 28659655, 2017). "To understand the biological role of miR-629 in pancreatic cancer progression, miR-629 mimic was transduced into the Capan-2 pancreatic cancer cell line, and we found that miR-629 overexpression significantly increased the population of CD44+CD24+ESA+ cells compared with the control cells." (PMID 29072689, 2017). "CD24 and CD44 are upregulated in human pancreatic cancer compared to chronic pancreatitis and may be related to the development of pancreatic cancer." (PMID 28659655, 2017). "Moreover, restoration of ESRP1 rescued the effect of miR-23a on CD44 splice isoform switching in pancreatic cancer cells." (PMID 29137308, 2017). "CD44 seems to be one of the most reliable markers of pancreatic cancer stem cells." (PMID 29156578, 2017). "Besides, the enrichment of the CD44+CD24+ESA+ cells was observed after the ionizing radiation treatment in human primary pancreatic cancer xenografts." (PMID 28245823, 2017). "These authors have isolated CD44+CD24+ESA+ cells from xenografts in immunodeficient mice of pancreatic cancer cells and have shown that these cells are highly tumorigenic and regenerated into host immunodeficient mice the original tumor histology and heterogeneity." (PMID 29156578, 2017). "In pancreatic cancer, investigation of cancer stem cell lineages enabled the identification of cell membrane markers such as CD44, CD24, epithelial specific antigen (ESA) and CD133 and the expression pattern of ALDH1A1 as an important biomarker of pancreatic cancer stem cells." (PMID 28671577, 2017). "Our previous findings and literature both suggest that HAb18G/CD147 activated EGFR signaling in pancreatic cancer cells may depend on CD44." (PMID 27556697, 2016). "In general, a CD44+/CD24+ phenotype has stem-cell properties in pancreatic cancer cells." (PMID 27689400, 2016). "In vivo blocking of CD44 s prevented PM in ovarian, gastric and pancreatic cancer." (PMID 27074785, 2016).
pancreatic cancer (continued). "OPN showed a positive association with coexpression of CD44/CD133 or LC3/ALDH1 in pancreatic tumors in this study; however the correlation was not strong." (PMID 26458814, 2015). "This suggests that targeting of CD44-overexpressing pancreatic CSCs may improve outcome in pancreatic cancer patients who undergo radiation therapy." (PMID 25954275, 2015). "CD44-positive cells constitute the resistant cell population, and CD44 could be a therapeutic target to overcome the drug resistance for pancreatic cancer." (PMID 26666511, 2015). "Thus, the observed impairment of pancreatic cancer cell behavior following IMP3depletion is likely due to inhibition of CD44-RhoA signaling." (PMID 25886367, 2015). "Moreover, a large body of epidemiological, clinical, and molecular evidence suggests that CD44 was overexpressed in pancreatic cancer cell lines and pancreatic tumors and plays an important role in the carcinogenesis and progression of pancreatic cancer." (PMID 26666511, 2015). "These may be the causes of the weak correlation between autophagy and single CSC marker expression (CD44 or CD133) in pancreatic tumor tissues." (PMID 26458814, 2015). "In general, a CD44+/CD24+/ESA+ phenotype has stem-cell properties in pancreatic cancer cells." (PMID 25118635, 2014). "For example, CD24+CD44+ESA+ pancreatic cancer cells possess CSC properties." (PMID 24955581, 2014). "Another study on pancreatic cancer stem-like cells demonstrated that isolated CD44+, CD133+, EpCAM+ cells of human pancreatic cancer behave as cancer stem-like cells, which show more aggressive behavior such as increased cell growth and migration, clonogenicity, and self-renewal capacity." (PMID 24821540, 2014). "c-MET and CD44 are co-expressed in a number of cancers, such as pancreatic cancer and CRC." (PMID 24823486, 2014). "This study systematically investigated whether CD44 expression patterns are involved in pancreatic carcinoma metastasis and prognosis." (PMID 24708709, 2014). "CD44 variants have been associated with tumor invasion and metastasis, but CD44 expression patterns have not been systematically investigated in pancreatic carcinoma." (PMID 24708709, 2014). "Also, ISIR-042 preferentially induced the cytotoxic effects on gemcitabine-resistant CD24+/CD44+ pancreatic cancer stem/progenitor cells from pancreatic cancer cell lines." (PMID 23301832, 2013). "It has also been observed that the exposure of human MIA-PaCa-2 pancreatic cancer cells expressing high levels of CD44 and CD24 stem cell-like markers to hypoxia and nutrient starvation induced the EMT programme and the expression of HIF-1α and autophagy-related genes." (PMID 23301832, 2013). "To test the in vivo relevance of the tumorsphere experiments, we implanted equal numbers of Bmi1 silenced and control lentiviral transfected CD44+CD24+ESA+ CSCs derived from primary human pancreatic cancer xenografts in the subcutaneum of NOD/SCID mice and measured the resultant tumor growth." (PMID 23437065, 2013). "This aggressive cell behavior was also demonstrated in CD44+/CD24+ pancreatic cancer cells." (PMID 23419168, 2013). "It was reported that CD44 is associated with FAK, paxillin, and Src activity, and the loss of CD24 expression significantly decreases cell proliferation, cell invasion, and metastasis nodules of CRC and pancreatic cancer in mice model." (PMID 23970932, 2013). "Therefore, repression of TP53INP1, LATS2 and CD44 revealed that each gene plays an important role in controlling pancreatic cancer growth." (PMID 23857777, 2013). "CD44 also plays a similar negative role in pancreatic cancer as its progression was accompanied by an almost complete loss of CD44 expression, due to alternative splicing of the CD44 pre-RNA." (PMID 22895640, 2012). "In addition, AHP3 and 3-Cl-AHPC inhibited growth and induced apoptosis in spheres derived from the CD44+/CD24+ (CD133+/EpCAM+) stem-like cell population isolated from the pancreatic cancer cell lines." (PMID 22570653, 2012).
pancreatic cancer (continued). "Later, CD44+/CD24+/ESA+ cells were referred to CSCs with 0.5%–1% of all pancreatic cancer cells." (PMID 22693526, 2012). "Cancer stem cells in pancreatic cancer are defined by the markers CD44, CD24, ESA and CD133." (PMID 22615799, 2012). "We further proceeded to test the efficacy of GSI on pancreatic tumor initiating CD44+/EpCAM+ cells." (PMID 23094026, 2012). "In pancreatic cancer, CD44+/CD24+ was demonstrated as potential phenotype to isolate CSCs." (PMID 22693526, 2012). "In vitro generated gemcitabine resistant pancreatic cancer cells were marked by high expression levels of CD44, while in another study increased CD24 and ESA expression, as well as activation of the c-MET receptor were also detected in gemcitabine resistant cells." (PMID 24213498, 2012). "Based on this prior work, we have chosen to analyze pancreatic tumor initiating CD44+/EpCAM+ cells." (PMID 23094026, 2012). "Interestingly, Pancreatic CD44+ESA+CD133+CD24+ CSCs also expressed CK19 (pancreatic cancer specific epithelial marker) and ABCG2 drug resistance genes." (PMID 23029396, 2012). "Previous studies have shown that pancreatic cancers and pancreatic cancer cell lines contain a small segment of cell population characterized by expression of CD133 or CD44/CD24/EpCAM positivity and which can be utilized to identify this cancer stem cell population." (PMID 22570653, 2012). "Furthermore, under GSI IX treatment, decline in the growth of pancreatic tumor initiating CD44+/EpCAM+ cells was observed in vitro and in a xenograft mouse model." (PMID 23094026, 2012). "Our in vitro results clearly showed that the inhibition of Notch signalling by GSI resulted in a dose-dependent growth attenuation of human pancreatic tumor initiating CD44+/EpCAM+ cells, down regulated the Notch target Hes1 and decreased EMT-related molecules." (PMID 23094026, 2012). "In pancreatic cancer, CD44+/CD133+ pancreatic CSCs been identified." (PMID 21304978, 2011). "This hypothesis is supported by a report which showed that a highly tumorigenic subpopulation of pancreatic cancer cells express cell surface markers CD44, CD24, and epithelial-specific antigen (ESA)." (PMID 19602232, 2009). "To investigate the potential role of miR-34 in pancreatic cancer stem cells, we examined whether miR-34 restoration could inhibit the CD44+/CD133+ cells and their self-renewal potential." (PMID 19714243, 2009). "Furthermore, CAFs can induce pancreatic cancer cell stemness through the SPP1/CD44 axis." (PMID 38445456, 2024). "In addition, more recent research has demonstrated that the interaction of HA and CD44 could be used for drug delivery in pancreatic cancer." (PMID 38783892, 2024). "Our results suggest that crosstalk via direct cell-to-cell transfer of cellular components foster chemotherapy-induced tumor evolution and that targeting of CD44 and MCT1(encoded by SLC16A1) may be useful strategy to prevent recurrence of gemcitabine-exposed pancreatic cancers." (PMID 36302783, 2022). "GABRP may contribute to CD44-induced gemcitabine resistance in pancreatic cancer." (PMID 35846884, 2022). "According to our model, CD44 may be a particularly attractive novel target in pancreatic cancer." (PMID 33578795, 2021). "In pancreatic cancer tissue, CD44 expression could therefore predict an ER." (PMID 34064540, 2021). "However, in the paraclone-derived pancreatic tumor similar expression patterns of Vimentin, N-cadherin, Integrin alpha V, CD44 and E-cadherin could be detected as in holoclone tumors." (PMID 30167093, 2018). "Moreover, clinical data have shown that patients with CD44+ pancreatic cancer have poor prognosis." (PMID 29179494, 2017). "Furthermore, TCGA data portal shows that human PDACs exhibit amplifications and mutations in ADAM10, MYC, VIM (vimentin), CD44, CCND1 (CyclinD1) and CTNNB1 (β-catenin), implying the importance of interfering with the signaling associated with these in prevention of pancreatic cancer." (PMID 26440150, 2015).
pancreatic cancer (continued). "We could therefore effectively distinguish each CD44 variant in pancreatic carcinoma tissue, rather than trying to identify thousands of complicated CD44 isoforms." (PMID 24708709, 2014). "CD44 has been identified as a marker for CSC identification in head and neck, prostate, ovarian, and pancreatic cancer." (PMID 39919692, 2025). "The FITC-conjugated EpCAM antibody (green), PE-conjugated CD44 antibody (red), PE-conjugated CD24 antibody (red), and PE-conjugated CD133 antibody (red) were used to characterize the pancreatic cancer stem cells." (PMID 39843495, 2025). "In many tumor models (including breast, lung, and pancreatic cancer), TGF-β1 has been shown to induce de novo HA synthesis and CD44 expression, which leads to the formation of the HA–CD44 complex and its interaction with kinase receptors such as EGFR." (PMID 41009438, 2025). "In pancreatic cancer, CSCs are characterised by some specific surface markers such as CD133 and CD44, distinguishing them from non‐stem cancer cells." (PMID 40903212, 2025). "Numerous studies have indicated that metastatic cells exhibit a CSC phenotype, characterized by markers such as ALDH+ and CD44+CD24− in breast cancer, CD26+ in colon cancer, and CD133+ in pancreatic cancer." (PMID 38891090, 2024). "In the present study, we evaluated the expression of selected CSC markers (CD133, CD44, and L1CAM) with immune checkpoint inhibitor (PD-L1) in pancreatic cancers." (PMID 39148690, 2024). "FH535 has also demonstrated anti-CSC activity in pancreatic cancer models, reducing clonogenicity and CD24−/CD44+ marker expression in vitro, as well as inhibiting metastasis and tumor growth in xenograft models." (PMID 38612911, 2024). "miR-34 targets key oncogenic factors like c-Met and influences the expression of CSC markers, such as CD44 and CD133, thereby inhibiting tumor formation and enhancing the sensitivity of pancreatic cancer cells to certain chemotherapies." (PMID 38139352, 2023). "For example, CD133+ cancer stem cells show high resistance to standard chemotherapy; CD44 sustains GEM resistance in pancreatic cancer cells; c-MET is also enhanced in GEM resistant (GR) pancreatic cancer cells and necessary for chemoresistance." (PMID 37327088, 2023). "Consistently, silencing of CD44 by siRNA suppressed MSN-driven reduction in MTT-based viability of PANC1 and Pa03C pancreatic cancer cells." (PMID 37699930, 2023). "The results showed that fisetin reduced the ratio of CD44+/CD24+ cells and increased that of CD44−/CD24− cells in human pancreatic cancer PANC1 cells." (PMID 37743465, 2023). "We measured the co-expression of CD24, CD44, c-Met, and CD326 to detect pancreatic cancer stem cells." (PMID 37308977, 2023). "In pancreatic cancer, overexpression of SOX2 induced cell proliferation and spherogenesis, promoted cancer cell dedifferentiation, and increased intracellular CD44, and ALDH expression levels." (PMID 37213675, 2023). "Both chemical and antibody-based strategies have been evaluated to target cell surface markers, and some phase I clinical trials have proceeded for CD44 and c-MET in pancreatic cancer." (PMID 37327088, 2023). "Although we have demonstrated the role of CD44 in this study, a recent report identified CD133 as a CSC marker in pancreatic cancer." (PMID 37108495, 2023). "Because aldehyde dehydrogenase 1 (ALDH1), CD44 and CD24 are well recognized cell surface markers for the stemness of pancreatic cancer cells, we next used these molecules as indicators to examine cell stemness." (PMID 37280198, 2023). "Recently, it has been seen that in pancreatic cancer cells, EMT phenotype induction seems to require the upregulation of CD44 expression with isoform switching of CD44v to CD44s expression." (PMID 36831554, 2023). "Next, we investigated the combined effect of CD24, CD44, and SLC16A1 expression on the prognosis of the pancreatic cancer patients." (PMID 36302783, 2022).
pancreatic cancer (continued). "In pancreatic cancer cells, overexpression of Sox2 not only increases the expression of ALDH1 and CD44 but also reduces the expression of epithelial marker E-cadherin through directly binding to the promoter of Snail." (PMID 35682836, 2022). "The results showed that high CD44 expression levels positively correlated with poor OS and RFS in pancreatic cancer patients." (PMID 36292918, 2022). "In pancreatic cancer, CSCs express CD24, CD44, CD133, aldehyde dehydrogenase 1 (ALDH1), and epithelial-specific antigen (ESA)." (PMID 35565450, 2022). "Both CD44 and GABRP were highly expressed in 178 pancreatic cancer patients which were validated in the starbase database." (PMID 35846884, 2022). "Those cells expressing CD44+, CD24+, and ESA (named pancreatic cancer stem cells) were responsible for tumor formation." (PMID 35800881, 2022). "We also showed that stemness marker CD44 and stromal marker α-SMA were positively correlated and progressively increased from the early to late stages of KPC mouse and human pancreatic tumor specimens." (PMID 36550571, 2022). "Based on these findings, the prognostic significance of CD44 and IGF1R expression in tumors from patients with pancreatic cancer were analyzed using the TCGA pancreatic cancer dataset." (PMID 35931675, 2022). "A Kaplan–Meier analysis was performed to reveal the correlation between CD44/CD44V3 expression and the prognosis of pancreatic cancer patients." (PMID 36292918, 2022). "For example, CD44 regulates MMP14 expression through Snail, leading to pancreatic cancer cell invasion." (PMID 35223528, 2022). "Functional assays including cell viability, colony formation, invasion, quantitative PCR and western blotting techniques were performed to validate the roles of CD44 and GABRP playing in mediating the gemcitabine resistance in pancreatic cancer cells." (PMID 35846884, 2022). "Shah and colleagues from M.D. Anderson showed that pancreatic cancer cell lines that selectively grew in culture media containing therapeutic doses of gemcitabine increased in expression of the stem cell markers CD24, CD44, and ESA." (PMID 36142575, 2022). "By analysing the TCGA database, we found that the expression of PCDH1 was positively correlated with CCND1, CCNE2, VEGFA, MET, CD44 and CD133 expression in pancreatic cancer tissues." (PMID 35864095, 2022). "In pancreatic cancer, CAFs can secret OPN/SPP1 to regulate the CD44 axis in cancer cells enhancing cancer stemness." (PMID 36319622, 2022). "Leptin overexpression promotes human pancreatic cancer xenograft growth and lymph node metastasis in mice, inducing the progression throughout the cell cycle and the expression of pancreatic cancer stem cell (CSC) markers (CD24+, CD44+, ESA+, ALDH+)." (PMID 33670492, 2021). "In pancreatic cancer cells, GLRX3 was increased in spheres compared to adherent cells and was also increased in CD24+/CD44+/ESA+ cells compared to CD24−/CD44−/ESA- cells." (PMID 34794402, 2021). "Among these transporter proteins, the significant overexpression of ABCB1 was found to be concomitant with the proliferation of resistant CD44 cells, suggestive of the regulatory role of CD44-ABCB1 interaction in GEM efflux in pancreatic tumor cells." (PMID 34453639, 2021). "The model simulations proposed the proteins AURKA, CD44, PAK1, STAT3, and TWIST1 as promising therapeutic targets for pancreatic cancer." (PMID 33578795, 2021). "Some markers have been described to define CSC populations in different cancer types; for instance, the combination of CD24 and CD44 markers delineates a common CSC population for colorectal cancer, liver cancer, pancreatic cancer, and others." (PMID 34774101, 2021). "Of xenograft cells receiving gemcitabine treatment, 32% were CD24+ CD44+ ESA+ cells, compared with 0.8% of control pancreatic cancer cells receiving vehicle treatment." (PMID 33995647, 2021).